IL1A (interleukin 1 alpha)
Diseases named in the same sentence as IL1A in open-access papers (continued):
Sharing a sentence is not in itself a finding about the gene and the disease.
infection (continued). "In terms of modulating early immune responses, IFN-γ, IL-1α, and IL-12p70 are crucial for infection control, while IL-13 and IL-18, found at higher levels in P4, assist in tissue repair and maintaining an anti-inflammatory environment." (PMID 40046233, 2025). "Conversely, Pad2−/− mice showed a downregulation of M1‐related genes (Il1a, Il1b, Tnf, Cxcl2, Ccl4, Il12a, Cxcl1, Il6) compared to WT mice after PA infection." (PMID 40087815, 2025). "A similar synergy in COX-2 upregulation was observed upon GF infection with oral pathogens in the presence of IL-1α, IL-1β, and interferon-α (IFN-α)." (PMID 40178270, 2025). "Analysis of macrophage‐related cytokines and chemokines found that Tnf, Il1b, Il1a, Ilrn, Il17ra, Cxcl1, Cxcl2, Ccrl2, Ccl3, Ccl4, and Ccl9 expression significantly increased over the course of infection." (PMID 41117166, 2025). "Both in the qPCR and the spatial outcomes, IL-1β had a multifold abundance over IL-1a (10-fold vs 1.5-fold expression during infection)." (PMID 40586608, 2025). "We used Luminex profiling of serum taken at 6 days post infection in the high dose cohort to analyse the relative levels of 9 cytokines and chemokines: IL-1α, IL-1ß, IL-6, IL-10, IL-12(p70), IL-17, CCL2/MCP-1, GM-CSF and IFN-γ." (PMID 40587585, 2025). "At 12-weeks post infection, only two AD genes Cdk5r1 and IL1a demonstrated statistically significant alteration of their expression compared with the sham-infected brain tissue." (PMID 40171450, 2025). "Studies with other respiratory pathogens like Legionella pneumophila show that AM-secreted IL-1α initiates and orchestrates the inflammatory response in the lungs of infected mice yet this remains to be examined during Mab infection." (PMID 40415550, 2025). "The lung, as the site of infection, showed consistent increases in IL-1α and IL-6, paralleling serum responses in coinfected mice." (PMID 41226526, 2025). "It has been suggested that IL-1α, released by damaged or stressed cells, establishes an “inflammatory loop” by recruiting inflammatory hematopoietic cells to the site of infection." (PMID 38400081, 2024). "As seen after LPS alone, expression of Il1a, Il1b and Tnfa increased 12 h after LPS exposure but declined during the first 2 days of infection." (PMID 39127259, 2024). "Of all the cytokines involved, interferon-alpha (IFN-α), interleukin 1 alpha (IL-1 α) and interleukin-6 (IL-6) are of particular interest in this type of infection." (PMID 39772252, 2024). "Treatment of L. major-infected Balb/c mice with recombinant IL-1α has proven effective in reducing lesion thickness and inducing a Th1 response during T cell priming (days 1 to 3 post-infection)." (PMID 39460345, 2024). "Despite the rapid clearance, A. baumannii infection resulted in neutrophil and inflammatory monocyte recruitment into the lungs and increased expression of the pro-inflammatory cytokines Il1a, Il1b and Tnfa at 12 h post infection." (PMID 39127259, 2024). "Beyond G-CSF, infections also induce the expression of a wide array of inflammatory cytokines by myeloid cells including IL-1α and IL-1β, interferons, tumor necrosis factor (TNF), and IL-6, the roles of which on bone have been recently reviewed [19•]." (PMID 38198032, 2024). "There was a notable and significant reduction in GzmB+RSV+CD8+ T cells suggesting that IL-1α acts on the recruitment of antigen-specific CD8+ T cells during infection." (PMID 38382577, 2024). "SAECs expressed the NLRP3 protein and at one day post-infection the level of cleaved IL-1α was increased." (PMID 38664396, 2024). "Compared with WT infection, deletion of yfiD led to the superior transcription of IL-1α (NP_034684.2), IL-1β (NP_032387), and IL-6 (NP_112445.1)." (PMID 38332126, 2024). "This suggested a large overlap in transcriptional change in the lung after infection or IL-1α instillation." (PMID 38382577, 2024).
infection (continued). "A functional difference between IL-1α and IL-1β has been reported for several infections, including group A Streptococcus39 and Toxoplasma gondii." (PMID 38382577, 2024). "Mice were injected intraperitoneally with anti-IL-1α, anti-IL-1β, or control antibody on days −1, 1, 3, and 5 of infection." (PMID 38382577, 2024). "On day 2 post infection, Il1a and Il1b expression were significantly higher compared to either LPS only or RSV only mice." (PMID 39127259, 2024). "Cells were transfected with Raptor or Rictor siRNA along with control siRNA 48 h prior to infection with R. rickettsii (SS); RNA was then isolated, and expression levels of IL-6, IL-8, and IL-1α were determined using their respective primer pairs." (PMID 38399700, 2024). "Of all the cytokines involved, interferon-alpha (IFN-α), interleukin-1α (IL-1α) and interleukin-6 (IL-6) are of particular interest in this type of infection." (PMID 39772252, 2024). "Necrotic cell death due to damage, stress, or infection induces the release of IL-1α into the surrounding milieu, which triggers the IL-1α-driven inflammatory loop." (PMID 38170734, 2024). "The mRNA expression of IFN-α, IL-1α and IL-6 showed divergent results depending on the virus used and the time of infection." (PMID 39772252, 2024). "These transcriptomic results are supported by the infection-induced secretion of IL1α, IL1β, IL8, and GM-CSF." (PMID 38902255, 2024). "IL-1α and IL-1β are both members of the IL-1 superfamily and are released at the early stages of infection." (PMID 39776597, 2024). "When evaluating IL-1α in lung homogenate supernatant following infection, we found that both Il1aΔ559,1 and wildtype mice had elevated levels of IL-1α that were not significantly different from one another." (PMID 38594380, 2024). "RSV infection also induced rapid and transient expression of Il1a, Il1b and Tnfa on day 1 post infection." (PMID 39127259, 2024). "Since IL-1α blockade during RSV infection reduced both weight loss and inappetence and IL-1α delivered i.n recapitulates some features of infection, we investigated the impact of IL-1α on the gut microbiome." (PMID 38382577, 2024). "The results showed that vL126A/ΔNLS infection lowered the transcriptions for IL-1α (P < 0.001, ***) and GM-CSF (P < 0.01, **) compared to vWT infection." (PMID 38547254, 2024). "IL-1α and IL-1β are pro-inflammatory and are produced during infection, tissue damage, or other inflammatory stimuli such as exposure to allergens, toxins, or stress." (PMID 38251210, 2024). "IL-1α and IL-1β are pro-inflammatory cytokines with similar biological properties, produced and released at the early stages of the immune response to infections." (PMID 36680273, 2023). "During early infection, TNFα, IL-1α, IL-6 and IL-8 are produced and result in stimulation of local and systematic pro/anti-inflammatory responses." (PMID 36726139, 2023). "Pulmonary IL-1α increased steadily over the 7 days post-infections, increasing over 100-fold compared with uninfected mice (p<0.0001 for both infections), and peaked at d7." (PMID 37724291, 2023). "We observed that infection of ATG5fl/fl BMDMΦ with R. typhi or R. rickettsii (SS) produced significantly lower levels of IL-1β or IL-1α cytokine, as compared to that of R. montanensis." (PMID 37819111, 2023). "TNF-mediated increase in Casp11 transcription can still be observed at 16 hours following priming (at the time of infection), while Il1a and Il1b transcription fades by that time." (PMID 37279255, 2023). "Previous study reported that infection by C. trachomatis in epithelial cells triggers release a range of cytokines that include IL-1α, granulocyte-macrophage colony-stimulating factor, (GM-CSF), IL-6, as well as IL-8." (PMID 36870960, 2023). "IL-1α and IL-1ß induction was initially modest during early infection but increased at late stages, potentially exacerbating inflammation." (PMID 37205380, 2023).
infection (continued). "While no human study has yet reported IL-1α regulation during WNV natural infection, IL-1α modulation during WNV infection varies across studies using experimental models." (PMID 36992514, 2023). "As expected, proinflammatory cytokines, such as IL-6, IL-8, and IL-1α, as well as the antimicrobial peptide hBD-2 are upregulated upon infection with M. furfur." (PMID 36835509, 2023). "Large amounts of IL-1α are stored in the stratum corneum keratinocytes to initiate a rapid inflammatory and immune response upon infection." (PMID 37237836, 2023). "During infection with the parasite T. gondii, microglia rapidly produced IL-1α, which was required for the protective recruitment of inflammatory T-cells." (PMID 37938547, 2023). "During infection with the parasite Toxoplasma gondii, microglia respond rapidly to produce the alarmin IL-1α, required to initiate immune cell infiltration and control of parasite infection." (PMID 37938547, 2023). "Upon skin injury, trauma, or infection, IL-1α is released promptly, inducing the local inflammation necessary to initiate wound healing." (PMID 36902387, 2023). "Infection of ATG5fl/fl-LysM-Cre BMDMΦ resulted in an increase of IL-1β or IL-1α cytokine levels for both R. typhi and R. rickettsii (SS)." (PMID 37819111, 2023). "After 14 days of infection, there were 257 genes with greater expression in nociceptor-ablated mice (e.g., Vegfa, IL1a, IL1b, and Tnf) compared to 219 genes with greater expression in control mice (e.g., Alox5, Car2, Ccl5, Elane, and Mmp8)." (PMID 37845223, 2023). "Our assays showed that infection of Beclin1fl/fl BMDMΦ with R. typhi or R. rickettsii (SS) produced lower IL-1β or IL-1α cytokine levels, as compared to that of R. montanensis." (PMID 37819111, 2023). "Recent studies using murine models have reported that in epicutaneous infection of S. aureus, PSMα induces the release of IL-1α and IL-36α from keratinocytes, leading to IL-17-dependent skin inflammation." (PMID 37275864, 2023). "IL-1α is one of the first cytokines produced and secreted by keratinocytes in response to an infection." (PMID 37237836, 2023). "Infection with virulent ASFV isolates often results in an exacerbated immune response, associated with elevated serum levels of pro-inflammatory cytokines (IL-1α, IL-1β, IL-6, TNF, CCL2, CCL5 and CXCL10)." (PMID 36680273, 2023). "Infection with P. aeruginosa resulted in increased IL-1α compared to uninfected controls, with dual-species infection resulting in a slight decrease in this marker compared to single-species infections (*P<0.05)." (PMID 36748431, 2023). "Pro-inflammatory cytokines, such as IL-1α, TNF-α, and IL-6 have also been linked to lymphoid hyperplasia in the initial stages of the infection." (PMID 36766408, 2023). "Conversely, infection significantly reduced levels of IL-1α, IL-2, IL-9, IL-10, IL-12 (p70), IL-13, IFNγ, IL-3, CCL4 (MIP-1β), CSF 2 (GM-CSF), CCL5 (RANTES), and TNFα." (PMID 37790429, 2023). "Infections with virulent ASFV isolates often results in increased levels of serum pro-inflammatory cytokines such as IL-1α and IL-1β." (PMID 36680273, 2023). "IL-1α functions as an alarmin by commencing the inflammatory cascade and drawing immune cells to the site of damage or infection." (PMID 37637634, 2023). "The infection with Mtb increased the production of IL-1β, IL-1α, IL-12, Interferon γ (IFN-γ), TNF, and the Granulocyte macrophage colony stimulating factor (GM-CSF)." (PMID 37375056, 2023). "It was demonstrated that infection of the skin models with C. albicans led to a significantly increased gene expression and secretion of IL-1α upon fungal recognition." (PMID 37237836, 2023). "The infection also induced IL-1α production, but inhibited CCL11 and IL-17 in both WT and deficient mice." (PMID 35479068, 2022). "IL-1α and IL-1β, the pro-inflammatory cytokines that play a central role during infection were also significantly decreased in treated mice." (PMID 36430961, 2022).
infection (continued). "Next, PBS- or Cl2MBP-liposome-treated WT mice were injected (i.v.)with BMDMs isolated from WT, Il-1β−/−, or Il-1α−/− mice prior to infection with R. typhi, R. rickettsii, or R. montanensis." (PMID 35130729, 2022). "The concentrations of IL-1a, IL-1b and GM-CSF in Rag2−/− mice remained at the same high level up to 20 days of infection, whereas the expression of IL-6 reached a peak on the 4th day, and then decreased to the initial level." (PMID 36016362, 2022). "We further tested the protein expression levels of pro-IL-1β and pro-IL-1α upon bacterial-infection of WT BMDMs and showed that pro-IL-1β levels were induced by all three Rickettsia spp." (PMID 35130729, 2022). "Our data showing differences in the early innate response, particularly IL-1α and IL-1β induction by AMs, in Mtb-HT and Mtb-LT infected mice suggest that AMs in Mtb-LT infection are inept at overriding their immunoregulatory environment." (PMID 35173157, 2022). "Mag-Pam2Cys_P48 treated moMΦ released higher levels of IL-1α, IL-1β, IL-1Ra, and IL-18 in response to infection with NH/P68 ASFV compared to 26544/OG10-infected and mock-infected controls." (PMID 36298767, 2022). "IL-1α is a pleiotropic cytokine and critical amplifier of inflammation in response to both infection and sterile cellular insults." (PMID 36505497, 2022). "Ciclopirox olamine was able to reduce IL‐1α release in infection with C. albicans, E. floccosum, and T. rubrum after 72 h." (PMID 35212482, 2022). "In agreement with our in vivo infection models, R. montanensis-infected WT BMDMs produced higher levels of IL-1α and IL-1β cytokines and displayed reduced bacterial loads during the course of infection, compared to R. typhi- or R. rickettsii-infected BMDMs." (PMID 35130729, 2022). "While the SARS-CoV-2 single-infection group showed moderate increases of IL-1α (at 7 dpi), IL-6 (at 2, 5, 7 dpi), and IFN-β (2 dpi), their expression levels were lower than those of the IAV single-infection group." (PMID 35107382, 2022). "The rGP19-immunized mice (50 μg and 100 μg) later infected with E. canis showed up-regulation of IL1a compared with naive mice on day 14 post-infection period, according to the T cell responses examined by flow cytometry." (PMID 36006302, 2022). "In fact, the genes encoding proinflammatory cytokines IL-1α, IL-6, TNF-α, and IL-8 are strongly downregulated compared to infection with H. pylori alone." (PMID 36394050, 2022). "The attenuated NH/P68 presented a reduced ability to infect moM1 compared with moMφ, and moM1 released IL-1α, IL-1β, and IL-18 in response to infection with this attenuated strain." (PMID 35215216, 2022). "Consistently, only the inhibition of IL1-α and IL-1-β toguether resulted in lower NO production in our in vitro infection model." (PMID 36569864, 2022). "Necrotic cell death in virus-mediated infection leads to the cell membrane rupture and subsequent release of IL-1α." (PMID 35619180, 2022). "A more detailed analysis of DEGs indicated on a strong immune response in MKN-28 cells after 2-h infection based on increased transcription of IL1A, IL8, IL24, CXCL2, CXCL3 and CCL20." (PMID 37193047, 2022). "Of interest, IL-1α levels in BAL were shown to be increased after infection, and during asthmatic inflammation, the AM pool at the early stages of the process depends on local proliferation." (PMID 35844510, 2022). "As in WT controls, early, infection-induced mRNA accumulation of COX-2 was enhanced in IL-1α−/−/IL-1β−/− mice." (PMID 35523455, 2022). "This was later supported by various cytokines, and chemoattractants, including a significant increase in IL-12p40 and IL-1α at 6- and 10-weeks post-infection." (PMID 36119114, 2022). "and showed that IL-1β and IL-1α release was significantly impaired compared to that in infections using viable Rickettsia spp., a phenotype more strongly observed in infections using R. montanensis." (PMID 35130729, 2022).
infection (continued). "Intriguingly, we observed that Listeria expressing the SPI-2 needle protein SsaG induced significantly increased IL-18 and robust IL-1α and IL-1β secretion compared to mock infection or WT Lm infection alone." (PMID 35073381, 2022). "Casp-1 deficiency (Casp-1−/−) caused a significant decrease in IL-1β production (green lines), while IL-1α secretion as well as the level of cell death remained unaffected during infection with all three Rickettsia spp." (PMID 35130729, 2022). "IL-1α is one of the early pro-inflammatory cytokines that is involved in recruitment of immune cells to the site of infection and it is important in protection against various pathogens." (PMID 35392409, 2022). "Accordingly, an increase in cytokine transcripts (Il6, Il8, Il1a, Il1b, and Ifng) were observed in Jamaican fruit bats upon infection." (PMID 35215832, 2022). "p75(NTR) was upregulated upon infection and affected innate immune cell behavior to producing the cytokines: IL-10, IL-6, and IL-1α." (PMID 34124260, 2021). "Candidalysin-driven IL-1α/β production, in turn, drives the proliferation of innate IL-17+TCRαβ+ cells and the expression of IL-17 needed to combat the infection." (PMID 33562334, 2021). "There is evidence to suggest IL-1α stimulation of keratinocytes reduces the adherence of S. pyogenes, thereby reducing the likelihood of invading bacteria establishing an infection." (PMID 35003136, 2021). "Immediately after Lm infection, IL-1α as well as IL-1β are produced in the spleen and liver, and exogenous IL-1α is known to decrease the bacterial burden by promoting neutrophil recruitment to infection sites." (PMID 34659211, 2021). "IL-1α is constitutively expressed in many cell types at a steady state, and can be induced in response to cell stress, injury, infection, or pro-inflammatory stimuli." (PMID 34943999, 2021). "Significantly higher levels of proinflammatory cytokines IL-1α, IL-1β, and IL-6 were observed in control mice during infection." (PMID 33514747, 2021). "Gene expression analysis revealed a significant induction in pro-inflammatory cytokine transcription in keratinocytes during infection with S. aureus with induction of IL1A (p < 0.05), IL6 (p < 0.01), and CXCL8 (p < 0.05) at early time points." (PMID 34944618, 2021). "In the event of cellular damage or programmed cell death IL-1α is released into the extracellular space and able to warn surrounding cells of damage or infection." (PMID 35003136, 2021). "Infection with V. montpellierensis induced significant elevation of sFasL (P = 0.0250) and IL-1α (P = 0.0137), IL-1RA (P = 0.0095), TNF-α (P < 0.0001), IL-1β (P = 0.0470)." (PMID 34230496, 2021). "In TLR2−/− mice, the pyrolysis-related proteins (GSDMD, IL-1α, and IL-1β) upregulated, which showed the immunocompetence in the infection of A. fumigatus." (PMID 34222495, 2021). "Multiple factors contribute to neutrophil recruitment from the circulation to the site of infection, including proinflammatory cytokines (such as IL-1α, IL-1β, TNF-α, and IL-6) and Cxcr2 chemokines (such as Cxcl1, Cxcl2, Cxcl5, and Cxcl8)." (PMID 34011393, 2021). "In this study, the percentage of IL-6, IL-21, IL-1α, IL-17 γδT cells increased significantly after infection (p < 0.05)." (PMID 33588839, 2021). "We observed a strong ExoU-dependent alarmin production in BALFs 6 h after infection, such as IL-1 family alarmins IL1α, IL-33 or IL-36γ." (PMID 34516571, 2021). "L. paracasei increases the levels of pro-inflammatory cytokines (IL1α and IL1β) and recruitment of immune cells before infection." (PMID 33897683, 2021). "As mentioned, four of these cytokines (IL-1α, IL-6, IL-8 and CXCL10) are associated with activation of the innate immune response to infection." (PMID 33657181, 2021).